TNF (tumor necrosis factor)
Diseases named in the same sentence as TNF in open-access papers (continued):
Sharing a sentence is not in itself a finding about the gene and the disease.
tumor (continued). "In the PDAC microenvironment, proinflammatory cytokines secreted by tumor cells and infiltrating immune cells, such as interleukin (IL)-1β, IL-6, and tumor necrosis factor (TNF)-α, have been shown to modulate PDAC progression and immune evasion." (PMID 32929072, 2020). "Anti-tumor CD8+ T lymphocytes promote anti-tumor immunity via production of pro-inflammatory cytokines such as TNFα and IFNγ and direct perforin/granzyme-dependent killing of tumor cells." (PMID 32917858, 2020). "We evaluated the plasma concentrations of Th1 (IL-2, IFN-γ, and TNF-α), Th2 (IL-4, IL-5, IL-6, and IL-10), Th9 (IL-9), and Th17 (IL-17A, IL-17F, IL-21, and IL-22) cytokines in tumor-bearing mice by flow cytometry." (PMID 32802733, 2020). "This indicated that FLP ointment significantly decreased the expression of IL-6, IL-1β, and TNF-α in exosomes, serum, lung, and tumour tissues." (PMID 32308722, 2020). "Macrophages in the tumor microenvironment are mainly M2-polarized TAMs and release anti-inflammatory cytokines (e.g., IL-1, TNF-a, IL-10)." (PMID 32222879, 2020). "In BNL and Hepa 1–6 tumor-bearing mice, treatment with TNF (1 μg/mouse), entolimod (1 μg/mouse) or their combination had no observable effect on tumor growth in either HCC mouse model when compared to untreated control groups." (PMID 32027657, 2020). "Despite that, among the CD8+ T lymphocytes recruited to the tumors, around 80% exhibited memory phenotype and were positive for IFN-γ and TNF-α, leading to tumor rejection." (PMID 33335860, 2020). "Its role in tumor growth and progression was also evidenced in human samples, where TNFα levels were directly correlated with CRC progression." (PMID 32722560, 2020). "Multiple proinflammatory cytokines are members of the tumor necrosis factor (TNF) superfamily and are involved in several physiological processes, including tumor prevention and host protection." (PMID 33322533, 2020). "Unlike CD8+ T cells, which requires a round of clonal expansion before unleashing its cytotoxic effects, NK cells can directly kill tumor cells, such as through the secretion of TNFα." (PMID 33262947, 2020). "Activation of the NF-κB pathway that is related to oncogenic cell signaling in epithelial cells has been identified as a critical pathway for TNF- α-induced tumor growth." (PMID 32937864, 2020). "A tumor sphere formation assay showed that 16B/TNF cells drastically increased self-renewal capacity as evinced by robust tumor sphere formation, while HOK-16B cells failed to form spheres." (PMID 31911577, 2020). "Even though the relevance of TNF in cancer has been proven, there are therapeutic effects and tumor advancing properties of its inflammatory response." (PMID 32228434, 2020). "For example, M1 macrophages conduct tumor killing by releasing lytic enzymes, TNF-α, oxygen and nitrogen intermediates, as well as mediating antibody-dependent cell-mediated cytotoxicity (ADCC)." (PMID 32499786, 2020). "The traditional, tumor-cytotoxic N1 phenotype has the potential to kill tumor cells, due to elevated levels of immune-activating factors (e.g., TNF-α, ICAM-1, FAS) and direct antibody-dependent cytotoxicity." (PMID 33171818, 2020). "TNF-α has been shown to promote destruction of tumor vasculature and synergize with liposome-mediated chemotherapy." (PMID 33292267, 2020). "Tumor cell-derived versican in turn promotes accumulation and secretion of proinflammatory TNFα and IL-6." (PMID 32265939, 2020). "MC-derived TNF-α possesses tumor-suppressive activity while IL-1β supports tumor progression and metastasis." (PMID 32086776, 2020). "The percent of tumor infiltrating CD8+ cells that expressed IFN-γ or TNF-α were similar in ALK5ΔCD8 and WT mice." (PMID 32273499, 2020). "In particular, it is shown that under a course of treatment with 3-week cycles where each drug is injected in the first day of either week 1 or week 2, injecting anti-TNF-α one week after anti-PD-1 is the most effective schedule in reducing tumor volume." (PMID 32310956, 2020).
tumor (continued). "Moreover, chemokine such as TNF can also induce activate inflammatory responses, and are implicated in the regulation of tumor development and growth via regulation of tumor-associated angiogenesis, by activation of host immunological responses or by direct inhibition of tumor cell proliferation." (PMID 32870935, 2020). "The high level of TNF-α can lead to the angiogenesis of tumor, promote the growth of tumor cells, and be beneficial to the infiltration and metastasis of cancer cells." (PMID 32936241, 2020). "Nitric oxide production by TANs, induced by TNF-α in the tumor microenvironment, promotes CD8+ T-cell appoptosis." (PMID 32722054, 2020). "The secretion of TNF-α, IL-6, and NO are elevated by M1 macrophages, which are typically described as tumor-killing macrophages." (PMID 32512803, 2020). "Dual cytokine loaded microspheres of IL-12/TNFα also induced increases in tumor-specific cytokine release from effector cells as compared to microspheres containing either cytokine alone or the combination of IL-12 and GM-CSF." (PMID 33178203, 2020). "IL-17 has been shown to enhance NK cell recruitment in human esophageal cancer through tumor-derived chemokines and NK cell cytotoxicity through the increased expression of activating receptors, perforin, granzyme B, TNF-α, and IFN-γ." (PMID 33584718, 2020). "The ELISA results indicated that PZH indeed decreased the levels of IL-6 and TNF-α in tumor tissue homogenates from HCC mice." (PMID 33344655, 2020). "IFN-γ, TNF-α, and granzyme B are typically associated with antitumor activity of cytotoxic CD8+ T cells via induction of enhanced tumor cell arrest and apoptosis 10, 58-60." (PMID 32206098, 2020). "Its i.v. administrations suppressed tumor growth in tumor-bearing mice by a higher TNF tumor accumulation." (PMID 33321882, 2020). "Meanwhile, interleukin 12 (IL-12p40) and tumour necrosis factor α (TNF-α) as indicators of DC activation elicited by ICD from dying tumour cells were determined by ELISA." (PMID 33009382, 2020). "Inflammatory cytokines abundant in cancer, including tumor necrosis factor α (TNF-α), have been shown to activate NF-κB constitutively in tumor cells." (PMID 33072583, 2020). "Consistently, we found that the percentage of single TNF-α+ CD8 T cells was the highest in the splenic CD8 T cells from tumor-bearing mice (CD8 T cells-TB Spleen)." (PMID 32916850, 2020). "Similar to NK cells, macrophages play an important role in innate host defense and in killing tumor cells by producing reactive oxygen/nitrogen species and pro-inflammatory cytokines such as tumor necrosis factor-alpha (TNF-α) and interleukin 6 (IL-6)." (PMID 33374978, 2020). "The modulation of TNF-α pathway to activate apoptosis in cancer cells toward the development of anti-tumor therapy has been widely investigated." (PMID 32850805, 2020). "Functionally, the triggering of LOX-1 by oxLDL was shown to induce TNF-α expression, tumor angiogenesis and tumor cell trans-endothelial migration and metastasis in prostate or breast cancers." (PMID 32133013, 2020). "Our study demonstrates that miR-381-3p expression varies among different types of human cancer cell lines, which negatively correlates with tumor cell sensitivity to TNF-induced apoptosis." (PMID 32411707, 2020). "Microbial infection can induce the production of cytotoxic substances that inhibit tumor growth especially tumor necrosis factor-α (TNF-α) through activation of macrophages and lymphocytes." (PMID 32850408, 2020). "Cytokines that affect other cancer-forming actions include TNF-α, which promotes inflammation and affects tumor formation." (PMID 32309219, 2020). "Conversely, when wt mice carrying a TNF‐unresponsive B16Bl6 tumor (B16‐dnTNF‐R1) were treated with TNF, the antitumor effect was similar to that observed with a parental B16Bl6 tumor." (PMID 31912630, 2020). "IFN-γ and TNF-α have been shown to contribute to anti-tumor activity by exerting anti-angiogenic effects." (PMID 32492770, 2020).
tumor (continued). "The accumulation of other pro-inflammatory cytokines within the tumor microenvironment including TNFα contributes to additional MSC accumulation and promotes the enhanced migration and invasiveness of cancer cells in breast and ovarian tumors." (PMID 32751163, 2020). "TNF-α is a cytokine with tumor necrosis activity that is secreted mainly by macrophages and has been recognized as an important host regulatory molecule." (PMID 32908915, 2020). "Although glucose starvation significantly reduced the tumour-killing capacity and the expression of granzyme B, TNF-α and IFN-γ of Teff cells, both glucose and inosine supplementation restored these properties in mouse and human Teff cells." (PMID 32694789, 2020). "The increased expression of the TNFα and IFNβ proteins was confirmed by intracellular flow cytometry in tumor cells at 24 and 48 h after 6 Gy irradiation." (PMID 33202881, 2020). "As with X-rays, exposure of MSC to UV light or heat induces increased release of anti-tumor or immunogenic factors, such as TNF-α and IFN-γ." (PMID 33023058, 2020). "The identified Enterococcus faecalis, was reported to enhance anti-oxidative activity and anti-tumor activity by NK cells and TNF-α." (PMID 33021988, 2020). "It has been demonstrated that TNF‐α as the critical trigger along with increased activation of JAK1/STAT1 plays a crucial role in tumor cell proliferation and invasiveness." (PMID 32677756, 2020). "TNF released by activated CD4+ T cells in tumor-bearing mice drives emergency myelopoiesis and generation of both monocytic and granulocytic myeloid cells with immunosuppressive properties." (PMID 33363012, 2020). "During the procedure of isolated limb perfusion, TNF is used for its vasodilating properties, allowing enhanced uptake of Mel by the tumour." (PMID 32419365, 2020). "By averaging z‐score expression levels per tumor, tumors with DDR mutation had lower expression levels of CTLA‐4, IFNG, TNF, FAS, and VTCN1, and higher expression levels of IL6, IL1B, and IL12A compared with the DDR wild‐type ones." (PMID 31991061, 2020). "Primary resistance to immunotherapy can also be the result of alterations in the TNF-α and IFN-γ signaling pathways protecting tumor cells against TNF-α- and IFN-γ-mediated cell growth regulation and death." (PMID 32290124, 2020). "In concordance with the upregulation of CD80 and TNFα displayed by MOv18 IgE-activated rat macrophages in tumour-bearing rats, both M0 and M2 human MDMs exhibited an upregulation of proinflammatory and immunostimulatory markers, following IgE cross-linking." (PMID 33081206, 2020). "We next evaluated multifunctional CD4+ and CD8+ T cells capable of simultaneously producing multiple effector Th1 cytokines and cytotoxic markers (IFN-γ, TNF-α, IL-2, and CD107a) because these cell types are strong effectors in tumor environments." (PMID 32486094, 2020). "Combination with anti–CTLA-4 led to tumor regression accompanied by enhanced T cell activity, increase in activated CD86+ monocytes in the tumor, augmentation of pro-inflammatory IFNγ, TNFα, and IL-6 and decrease in immunosuppressive MCP-1 and IL-10 cytokines." (PMID 32793228, 2020). "In skeletal muscle, CLA enhanced tumor- induced gene expression of inflammatory markers TNF- α, IL-6 receptor and F4/80." (PMID 33415123, 2020). "TAMs influence on tumor cell invasiveness when tumor-released TNF-α elicits the expression and secretion of CCL8 from TAMs." (PMID 32499786, 2020). "Because anti‐tumor effects of TNF and IFNγ had been observed in pre‐clinical models, both cytokines were tested in the clinic when recombinant proteins became available." (PMID 31916677, 2020). "And TNF to a greater extent begins to react with moderate- and low-differentiated tumor tissue (G1 versus control p = 0.1; G2 versus control p < 0.001; G3 versus control p = 0.004)." (PMID 32963755, 2020).
tumor (continued). "Blocking RAGE results in inability of TNFα, TNFα/IFNγ, and tumour‐CM to activate the signalling pathways leading to muscle protein degradation." (PMID 32159297, 2020). "In a study addressing not only TNFα but also IL-1β, the two cytokines were shown to increase tumor cell proliferation in a metastasis-suppressed model of a TNBC cell line and in combination with IL-6 and CXCL8 also of luminal-A cells." (PMID 33585241, 2020). "By IHC analysis, we demonstrated that the expression levels of CD68, IL-6 and TNF-α in tumor cells of FOBT-positive patients were significantly higher than those in FOBT-negative patients." (PMID 33643891, 2020). "IL-1β, while promoting increased synthesis of IL-2, IL-6, and TNF-α, also acts as a tumor growth promoting molecule in conditions of chronic inflammation." (PMID 33718121, 2020). "Although administration of TNFα significantly decreased the tumor growth, but many side effects were observed in the studies." (PMID 32219066, 2020). "TNF mRNA expression was also increased in tumors from CRC patients compared to adjacent non-tumor tissues in colons from the same patients (P = 0.034)." (PMID 32171282, 2020). "Intratumoral treatment resulted in dose-dependent increases in IL-6 and TNFα in both tumor and serum at early time points, yet, the magnitude and duration of the response were substantially higher within tumors." (PMID 32483165, 2020). "Even though SM are well tolerated, they have limited single agent efficacy in most cancers due to the low concentration of TNF in the tumour microenvironment that would drive RIPK1‐dependent cell death in the absence of cIAPs." (PMID 32419365, 2020). "This phenomenon results in increased concentration of numerous cytokines, such as IL-6, IFN-γ, and TNF-α, within the tumor microenvironment and subsequent cancer progression." (PMID 33260925, 2020). "The NF-κB pathways are important during cytokine activation as they regulate tumor cell survival during early tumor promotion and induce the transcription of genes for proinflammatory cytokines, such as TNF-α and IL-6." (PMID 32156252, 2020). "NVP-LCL161 is a first-in-class oral SMAC mimetic that induces degradation of cIAP1 and has demonstrated single-agent activity in human tumor xenograft models, with basal production of TNF-α and NF-κB inhibition as a common mechanism." (PMID 32989221, 2020). "The secretion of TNF-α cytokines in tumor microenvironment can accelerate the growth and spread of cancer cells." (PMID 33184404, 2020). "They exhibit pro-inflammatory and anti-tumor properties by releasing various types of pro-inflammatory cytokines and chemochines, such as Tumor Necrosis Factor (TNFα), Interleukin-6 (IL-6), Interleukin-1 Beta (IL-1β) and Nitric Oxide Synthase (INOs)." (PMID 32471272, 2020). "We included both anti- and pro-inflammatory cytokines involved in tumor suppression such as TNF-α, IL-1β, and tumor promotion such as IL-10, CCL22, CXCL5, and TGF-β (selection of cytokines based on ref.)." (PMID 33267818, 2020). "Inflammation occurs in the tumor microenvironment, which in turn accumulates a large number of cytokines, chemical mediators and enzymes, such as TNF-a, IL-6, VEGF, iNOS, Cox-2, and MMP-9, for mediating inflammation and driving its malignant transformation." (PMID 31343435, 2020). "Minimal toxicity was noted when tumour‐bearing rats were treated with TNF/Mel, equating to grade I reactions (Fig EV3F)." (PMID 32419365, 2020). "Though a high level of TNF-α was produced in tumors and the tumor size was reduced, the injected macrophages were returned back to the M2-like mode in tumors by secreting anti-inflammatory cytokines and lipid mediators in the tumoral microenvironment." (PMID 32089766, 2020). "Considering originally potential mechanisms of TNFα induced tumor necrosis, we demonstrate that TNFα has protumor activity under bevacizumab administration in the tumor microenvironment." (PMID 33214550, 2020).
tumor (continued). "Some cytokines and growth factors have been reported to increase the concentration of checkpoint ligand PD-L1 on tumor cells, such as interferon-γ (IFNγ), tumor necrosis factor α (TNFα), or epidermal growth factor (EGF)." (PMID 33233528, 2020). "It is well established that the tumor microenvironment is enriched with various pro-tumorigenic stimuli, such as tumor necrosis factor-α (TNF-α), inflammatory cytokines, and growth factors, which constitutively activates NF-κB signaling and cell proliferation." (PMID 32961826, 2020). "The delay in tumour growth of animals treated with TNF/Mel/SM translated into significantly prolonged survival when compared to the standard‐of‐care TNF/Mel (median 24.5 vs. 18 days, P = 0.0063, log‐rank test)." (PMID 32419365, 2020). "TNF-α, a well characterized inflammatory factor, has strong tumor-initiating effects at a low and constant dose." (PMID 32019974, 2020). "A tumor promotion mechanism by TNF-α is based on the activation of the NFkB pathway and the generation of reactive oxygen species (ROS) and reactive nitrogen species (RNS), which can induce DNA damage, thereby facilitating tumorigenesis." (PMID 32283655, 2020). "Low levels of IL-1β, TNF-α, and IL-6 stimulate angiogenesis, and IL-6 modulates polarization of tumor-associated macrophages (TAM) from M1 (a tumor-eliminating phenotype) to M2 (an anti-inflammatory and tumor-promoting phenotype)." (PMID 33195486, 2020). "For each pair of (anti-PD-1, anti-TNF-α) in some range we marked on the color columns the tumor volume reduction rate (TVRR) at the end of the treatment." (PMID 32310956, 2020). "Another theory is that GGT is induced by inflammatory cytokines, such as tumor necrosis factor-α and interferon, which are involved in carcinogenetic processes and the regulation of the tumor microenvironment." (PMID 32695241, 2020). "CpG-ODN triggers TAM to release a copious amount of TNF that leads to a rapid tumor hemorrhagic necrosis." (PMID 32962159, 2020). "Both tumor and stromal cells of solid tumors secrete TNF-α and, interestingly, tumor promoting but also inhibitory effects were described." (PMID 32244723, 2020). "Yet, the functional role of downstream targets of SMG7 with respect to TNFα and tumor biology is poorly understood." (PMID 32602581, 2020). "Clinical studies that specifically direct cytokines such as TNF or IFNγ to the tumor endothelium via peptides or single‐chain antibodies are already underway." (PMID 31916677, 2020). "This disparity likely explains entolimod’s failure to protect these tumor cell types from TNF toxicity in our experiments." (PMID 32027657, 2020). "To investigate the influence of exogenous IL-33 on pro-inflammatory factors, such as IL-6, IL-1β, and tumour necrosis factor (TNF)-α, we measured their mRNA expressions, which are known to stimulate tumour proliferation and angiogenesis." (PMID 33308251, 2020). "Many studies have reported that TNF-α pathway plays important roles in regulating tumor proliferation, migration, invasion and angiogenesis, its aberrantly expression poses consequential impact on the TME." (PMID 32850805, 2020). "Further, T cell cytokines such as TNF can induce NGFR expression on tumor cells leading to the acquisition of MART-1/gp100 T cell resistance." (PMID 32770055, 2020). "The typical tumor volume as well as weight of TNF-α- treated LV5-PTX3 tumors was distinctly lesser than that of TNF-α-treated LV5-NC tumors." (PMID 32194791, 2020). "According to these results, the pro- or antitumor response of TNF-α within the tumor microenvironment depends not only on the local concentration but also on its expression site in the tumor." (PMID 32283655, 2020). "The inflammatory response increases following IAP blockade, thereby stimulating CTLs and mononuclear/macrophage TNF production and enhancing tumor cell killing." (PMID 32000802, 2020).